KLF6 (KLF transcription factor 6)
Diseases named in the same sentence as KLF6 in open-access papers (continued):
Sharing a sentence is not in itself a finding about the gene and the disease.
chondrosarcoma (1 paper, 2021). A malignant cartilaginous matrix-producing mesenchymal neoplasm arising from the bone and soft tissue. "In the present study, we for the first time revealed that KLF6 was downregulated and exerted tumor-suppressing function in chondrosarcoma." (PMID 33431838, 2021). "To investigate the involvement of KLF6 in the progression of chondrosarcoma, we then measured the expression of KLF6 in normal tissues and tumor tissues of human chondrosarcoma by qRT-PCR." (PMID 33431838, 2021). "To ascertain the association among KLF6, EZH2, SP1, and SNHG6 during the progression of chondrosarcoma, we then measured the expression of EZH2 and SP1 in KLF6-overexpressing SW1353 and HCS2/8 cells." (PMID 33431838, 2021). "Collectively, these experiments demonstrate that KLF6 expression was downregulated in chondrosarcoma." (PMID 33431838, 2021). "To pinpoint the sophisticated regulatory function of KLF6 on SNHG6 in the promotion of chondrosarcoma, we further knocked down KLF6 in both SW1353 and HCS2/8 cells by shRNA based on SNHG6 silencing." (PMID 33431838, 2021). "To reinstate the expression of KLF6 in chondrosarcoma cells, we then overexpressed KLF6 in SW1353 and HCS2/8 cells by lentivirus, and western blotting experiment demonstrated that KLF6 expression was significantly upregulated." (PMID 33431838, 2021). "Mechanistically, augmented SNHG6 recruited EZH2 and inhibited the transcription of tumor-suppressor gene KLF6, which thus promoted the tumorigenesis of chondrosarcoma." (PMID 33431838, 2021). "Afterwards, we performed MTT assay, colony-formation assay, transwell migration, and invasion assay to evaluate the influence of KLF6 overexpression on the proliferation, migration, and invasion of chondrosarcoma cells." (PMID 33431838, 2021). "Furthermore, the migration and invasion capacities of chondrosarcoma cells were also impaired by KLF6 overexpression." (PMID 33431838, 2021). "Overall, these results substantiated that KLF6 overexpression could inhibit the proliferation, migration, and invasion of chondrosarcoma cells." (PMID 33431838, 2021). "Therefore, recovering the normal expression of KLF6 in tumor cells was one critical way to suppress the proliferation, migration, and invasion of chondrosarcoma." (PMID 33431838, 2021). "In the present study, we for the first time found that SP1 induced the upregulation of SNHG6, which then led to the suppression of KLF6 by recruiting EZH2 and promoted the tumorigenesis of chondrosarcoma." (PMID 33431838, 2021). "In summary, this study reveals that SP1-induced SNHG6 forms a positive loop to facilitate the carcinogenesis of chondrosarcoma through the suppression of KLF6 by recruiting EZH2, which manifests the oncogenic function of SNHG6 in chondrosarcoma." (PMID 33431838, 2021). "SNHG6 suppressed the transcription of tumor-suppressor gene KLF6 through EZH2, which further promoted the tumorigenesis of chondrosarcoma." (PMID 33431838, 2021). "This novel mechanism is the first report about the function of SNHG6 in chondrosarcoma and revealed that lncRNA SNHG6 and KLF6 played an essential role during the progression of chondrosarcoma." (PMID 33431838, 2021). "At last, we examined the relative expression of KLF6 in normal chondrocytes and several available chondrosarcoma cell lines by qRT-PCR; consistently, KLF6 expression was reduced in all the chondrosarcoma cell lines, and SW1353 and HCS2/8 cells showed the least expression of KLF6." (PMID 33431838, 2021).
chronic pancreatitis (1 paper, 2010). A chronic inflammatory process causing damage and fibrosis of the pancreatic parenchyma. "To evaluate KLF6 protein expression, we obtained another independent dataset of 50 patients represented on a TMA with matched normal, chronic pancreatitis, and PDAC (UNC2)." (PMID 20644708, 2010).
delirium (1 paper, 2018). A disorder characterized by confusion; inattentiveness; disorientation; illusions; hallucinations; agitation; and in some instances autonomic nervous system overactivity. "In CSF, KLF6 (Kruppel-like factor-6) was elevated in patients with delirium." (PMID 30367354, 2018). "Only one protein, KLF6, differed between the postoperative CSF levels in patients with and without delirium at uncorrected p < 0.05." (PMID 30367354, 2018).
ductal carcinomas (1 paper, 2010). "The analysis of 48 ductal carcinomas revealed a significant population expressing KLF6 predominantly in the nuclear compartment (X2p = 0.005; Fisher p = 0.003)." (PMID 20126619, 2010). "Nevertheless, the obtained results suggest that a high percentage of ERBB2-overexpressing ductal carcinomas may express KLF6 at the nuclear compartment during early stages of development." (PMID 20126619, 2010). "In contrast, ERBB2-negative ductal carcinomas showed a significant lower KLF6 stain scores (p = 0.007; student t test) and absence of nuclear staining compared to ERBB2-overexpressing ductal carcinomas (score mean 1.9 versus 2.5, respectively)." (PMID 20126619, 2010).
embryonal rhabdomyosarcoma (1 paper, 2013). A poorly circumscribed morphologic variant of rhabdomyosarcoma. "Many myopathies and muscle loss disorders have been linked with increased TGFβ signaling and hence, our findings identify KLF6 as a potential therapeutic target for such pathological conditions, as well as for cancers, such as embryonal rhabdomyosarcoma, where TGFβ promotes cell proliferation." (PMID 23547561, 2013).
Fibroadenoma (1 paper, 2010). A benign tumor of the breast characterized by the presence of stromal and epithelial elements. "Interestingly, the stain intensity was consistently higher than of a fibroadenoma tissue sample, which expressed low levels of KLF6 that was detected systematically in the cytoplasmic compartment." (PMID 20126619, 2010).
hypertrophic cardiomyopathy (1 paper, 2024). A condition in which the myocardium is hypertrophied without an obvious cause. "For hypertrophic cardiomyopathy, the analysis showed a direct interaction, specifically co-expression and text mining, between IL-6 and KLF-2, KLF-4, and KLF-6." (PMID 38672763, 2024).
hypertrophy (1 paper, 2021). Hypertrophy is the increase in the volume of an organ or tissue due to the enlargement of its component cells. "Additionally, differentiated spliced TFs also function in cardiac fibrosis (e.g., KLF6), angiogenesis (e.g., VEZF1), cardiac structure and contractile function (e.g., VEZF1), cardiac hypertrophy, inflammation, and regulatory T-cell homeostasis (e.g., ZFP91)." (PMID 34977163, 2021).
inflammatory bowel disease (1 paper, 2018). A spectrum of small and large bowel inflammatory diseases of unknown etiology. "Further, we found known associations between KLF6, NR3C1, XBP1 and HSF1 with inflammatory bowel disease further validating our analyses." (PMID 30184180, 2018).
intrahepatic cholestasis (1 paper, 2024). A cholestasis characterized by impairment of the bile flow caused by obstruction located in the liver. "Vincamine alleviated hepatic dysfunction during ANIT-induced intrahepatic cholestasis through its anti-inflammatory and antioxidant efficacies by the modulation of NF-kB/PDGF/klf6/PPARγ and PI3K/Akt pathways." (PMID 38761209, 2024).
invasive breast carcinoma (1 paper, 2020). A carcinoma that infiltrates the breast parenchyma. "In addition, expression of KLF6 and E-cadherin (encoded by CDH1) was significantly downregulated in human invasive breast carcinoma and a significant positive relationship between KLF6 and E-cadherin was observed." (PMID 32733026, 2020).
keratoconus (1 paper, 2013). A degenerative, structural disorder of the eye, characterized by a cone-shaped protrusion of the cornea. "Interestingly, KLF6 expression also is elevated in keratoconus, a progressive disease associated with thinning and scarring of the cornea." (PMID 23533700, 2013).
kidney cancer (1 paper, 2021). Primary or metastatic malignant neoplasm involving the kidney. "In kidney cancer, KLF6-SE promotes the expression of KLF6 and then activates PDGFB to promote lipid metabolism, leading to the growth of ccRCC25." (PMID 33712565, 2021).
lung squamous cell carcinoma (1 paper, 2023). "KLF6 and JUNB were downregulated in LUAD and lung squamous cell carcinoma (LUSC) (p < 0.05)." (PMID 37405258, 2023).
lupus (1 paper, 2024). "Many genes contained in the Hallmark IFN-α response and Hallmark TNF-α signaling pathways, including IFI27, IFI44, RELB, KLF6, and CD83, had significantly higher expression in lupus: We verified transcriptional changes in the naive compartment by quantitative PCR (qPCR)." (PMID 39688922, 2024). "However, a much larger set of TFs contained in the TNF-α signaling gene set appeared among the active TFs in lupus cells; these include FOSL1, KLF6, RELB, BHLHE40, EGR3, and SMAD3." (PMID 39688922, 2024).
lymphedema (1 paper, 2021). Excess fluid collection in tissues, causing swelling. "Nevertheless, preadipocytes derived from lymphedema subjects exhibited differential expression of GDF15, the marker of mitochondrial stress, and of KLF4, KLF6, INHBA and ZNF423, i.e. genes implicated in adipogenesis, when compared with cells from healthy women." (PMID 33854130, 2021).
osteoarthritis (1 paper, 2008). A noninflammatory degenerative joint disease occurring chiefly in older persons, characterized by degeneration of the articular cartilage, hypertrophy of bone at the margins and changes in the synovial membrane. "Proteins such as SOX11, FGF23, KLF6, WWOX and GDF15 not implicated previously in the genesis of osteoarthritis were identified." (PMID 19011694, 2008). "In addition we detected novel proteins that were deregulated in osteoarthritis, such as SOX11, FGF23, KLF6, WWOX and GDF15." (PMID 19011694, 2008).
pancreatic adenocarcinoma (1 paper, 2021). "AS events of FGFR-2, SPAR, COL6A3 in pancreatic adenocarcinoma have also been previously reported 30-32, and an increase in AS of the KLF6 cancer suppressor gene is associated with pancreatic adenocarcinoma prognosis and tumour grade 33." (PMID 33976726, 2021).
pulpitis (1 paper, 2022). Inflammation of the dental pulp. "The KLF6 and P21 staining intensities were also strong in the odontoblasts around the reparative dentin in the direct capping and pulpitis groups." (PMID 35422483, 2022).
schizophrenia (1 paper, 2024). A major psychotic disorder characterized by abnormalities in the perception or expression of reality. "Transcription factor activity analysis also revealed a panel of seventeen transcription factors with more significant activity in males; NFKB1, FOS, and KLF6 had been linked to schizophrenia previously, although none had been specifically linked to male schizophrenic patients." (PMID 39068467, 2024).
skin aging (1 paper, 2023). The gradual irreversible changes in structure of skin that occur as a result of the passage of time.. "Therefore, it can be suggested that UVA radiation can lead to skin aging by the downregulation of KLF6, and that the activation of KLF6 may be a major anti-aging approach." (PMID 36832881, 2023). "They found that the downregulation of KLF6 and HES1 were the driving force involved in skin aging." (PMID 36832881, 2023).
Stroke (1 paper, 2021). Sudden impairment of blood flow to a part of the brain due to occlusion or rupture of an artery to the brain. "Alongside expression of RTN4A, comprising 76% total astrocytes in the injured cohort and 21% in control, we observed robust expression of GAP43, CD44 and KLF6, with both the percent of nuclei expressing these genes and the overall level of expression significantly increased after stroke." (PMID 34824275, 2021).
tendinopathy (1 paper, 2021). "Targeting Krüppel-like factor 6 (KLF6), miR-148a-3p could affect the expression of TSP-4 in tendonocytes, and is closely related with Tsp-4 levels in tendinopathy tissues, which also promoted endothelial cell (EC) angiogenesis." (PMID 34277629, 2021).
tumor (182 papers, 2003 to 2025). "The role of KLF6 in tumors was dichotomous: wild-type KLF6 (wtKLF6) acts as a tumor suppressor gene that inhibited tumor growth; while its splice variant KLF6-SV1 promoted tumor progression, drug resistance, and metastasis." (PMID 40406148, 2025). "KLF6’s downregulation in high-grade tumors aligns with its tumor suppressor role and association with poorer outcomes." (PMID 40500522, 2025). "The tumor suppressor KLF6 similarly generates an oncogenic splice variant, KLF6-SV1, which antagonizes wild-type KLF6, promoting tumor growth and leading to unfavorable clinical outcomes across multiple cancers." (PMID 41465349, 2025). "Authors concluded that miRNA-200b inhibited Kruppel-like factor 6 (KLF6), eventually decreasing the M1 polarization and causing immunosuppression, leading to the malignant phenotype of tumor cells." (PMID 39195233, 2024). "In contrast, the SV2 KLF6 variant is down-regulated in human HCC samples compared to adjacent non-tumor liver tissue." (PMID 35008179, 2021). "Abundant data indicate that wild-type KLF6 (WtKLF6) is a classical tumor suppressor and is frequently mutated in many cancers." (PMID 33816511, 2021). "KLF6 is a Krüppel-like transcription factor with tumor suppressor functions, and is associated with chemoresponse and prognosis in OC patients." (PMID 32332753, 2020). "Stemming from this prostate finding, the KLF6 mutational status, expression level and tumour-suppressive roles were extensively studied in various cancer types." (PMID 32998281, 2020). "Remarkably, KLF6 encodes multiple protein isoforms derived from alternative splicing, most of which are intimately involved in tumorigenesis and tumor progression." (PMID 31065692, 2019). "KLF6-SV1, a splice variant of KLF6, antagonizes the wild-type KLF6's tumor suppressive effects in many cellular processes, including proliferation, invasion and in vivo tumor growth." (PMID 31632477, 2019). "The precise underlying mechanism by which KLF6 exerts its tumor suppressor role involves a variety of complex pathways." (PMID 31824948, 2019). "KLF6 can be expressed as several differentially spliced variants (SV-1, SV-2 and SV-3), some of which have been linked to tumour progression." (PMID 30858363, 2019). "Klf6 has previously been studied as a tumor suppressor in prostate, ovary, and liver, and Klf4, Klf5, and Klf6 are also implicated as regulators of viability." (PMID 27213272, 2016). "KLF6 has been mainly implicated as a tumor suppressor gene, frequently inactivated in a variety of human cancers." (PMID 21799854, 2011). "This expression pattern completely matches with the role as tumor suppressor described for KLF6 since mutations of klf6 gene were associated to different human neoplasms." (PMID 20126619, 2010). "The tumor suppressor function of KLF6 has been widely confirmed through its loss and mutation in a number of cancers and the ability to reduce colony formation in cultured cells." (PMID 20844588, 2010). "KLF6 encodes the zinc finger protein that acts as a tumor suppressor." (PMID 34194463, 2021). "Loss-of-heterozygosity (LOH) analysis revealed that KLF6 inactivation conformed to the Knudson’s two-hit hypothesis, thus classifying KLF6 as a tumour suppressor." (PMID 32998281, 2020). "Finally KLF6 is a tumor suppressor that is down-regulated or mutated in several types of cancers, suppressing tumor growth through the activation of p21 and inducing apoptosis in prostate cancer." (PMID 32753692, 2020). "Therefore, in the present study, we investigate the expression levels of the wild-type KLF6 and its oncogenic variants as well as the copy number variation in tumor biopsies and normal nasopharyngeal mucosae of Tunisian patients." (PMID 29854578, 2018).
tumor (continued). "In BTSC23 cells, KLF6-wt caused accumulation of cells in G2 phase, which could reflect the different nature of this tumor cell type." (PMID 28166199, 2017). "Interestingly, an alternative mechanism to downregulate KLF6 was found to involve the generation of three splice variants (SV1-3) with antagonistic effects on the wild type KLF6 tumor suppressor function." (PMID 24429391, 2014). "Recent studies have reported that KLF6 could serve as a new molecular marker candidate for tumor prognosis and a potential therapeutic target, because abnormal KLF6 expression was associated with a poor clinical prognosis, cancer recurrence, and drug resistance." (PMID 31723124, 2019). "In accordance with these findings, individual and combined knockdown of FOSL2 and KLF6 compromised the 5-FU resistance of HCT15-FR cells in a nude mouse subcutaneous tumor model." (PMID 40082673, 2025). "In M1 macrophages (anti-tumor), LncRNA-Xist is upregulated, maintaining the M1 phenotype by inhibiting miR-101, which in turn allows the expression of C/EBPα and KLF6, two transcription factors that support M1 polarization." (PMID 40330466, 2025). "In contrast, miR-101 is highly expressed in M2 macrophages (pro-tumor) and suppresses C/EBPα and KLF6, promoting M1-to-M2 polarization." (PMID 40330466, 2025). "To establish the direct involvement of KLF6 in the anti-tumor effect of LCACs, we knocked down KLF6 in HCC cells and found that inhibitory effect of LCAC-16:0 on the growth of HCC cells was abolished upon KLF6 knockdown, signifying that LCACs act through KLF6." (PMID 40370557, 2025). "For instance, KLF6 functions as a tumor suppressor, for instance, controlling metastasis, invasiveness, and cell proliferation." (PMID 41155227, 2025). "For a deeper understanding of the oncogenic mechanisms of the C0 MAFF+ tumor cell subtype, we analyzed the TFs within this subtype and identified the top five active TFs: KLF6, ATF3, JUN, FOS, and FOSB." (PMID 40936936, 2025). "The overexpression of circMTO1 levels increased KLF6 levels, implicating circMTO1 in miR-630 activity, which then inhibits KLF6, facilitating tumor progression." (PMID 40868849, 2025). "miR-200b achieves this by suppressing the expression of Kruppel-like factor 6 (KLF6), a tumor suppressor that normally inhibits M2 polarization." (PMID 40330466, 2025). "KLF6 is a known tumor suppressor involved in key processes such as cell cycle regulation, apoptosis, and differentiation." (PMID 40557319, 2025). "Among these biomarkers, KLF6 demonstrated the most pronounced reduction in expression with tumor progression, as evidenced by significant decreases in both stage and grade-stratified analyses." (PMID 40500522, 2025). "Further functional studies showed that LCACs exerted anti-tumor activity in HCC by increasing histone H3 acetylation in the KLF6 promoter region." (PMID 40370557, 2025). "KLF6 serves as an important tumor suppressor gene frequently downregulated in multiple human cancers." (PMID 39263604, 2024). "To further investigate the impact of key genes on tumor progression, we performed single-cell analysis and found KLF6 was highly expressed in immune cells and strongly elevated in tumor cells." (PMID 38773440, 2024). "For example, PITRM1-AS1 has recently been shown to interact with KLF6, a transcription factor and tumor suppressor dysregulated in several cancers." (PMID 37444464, 2023). "KLF6 is a tumor-suppressor gene that reduces cancer cell growth in culture and tumors in xenograft mice." (PMID 37239940, 2023). "Although the mechanisms of generating KLF6 splice variants in cancer are not fully understood, an association exists between these splice variants’ mRNA expression and PDAC tumor grade." (PMID 37239940, 2023). "Through further transcriptome analysis of clinical PDAC data, KLF6 splice isoform mRNA expression was positively correlated with tumor grade and survival outcome." (PMID 37239940, 2023).